RNVU1-19 (RNA, variant U1 small nuclear 19)
Synonyms: vU1.19; RNU1-126; vU1.13; RNU1-147; RNVU1-13
Gene: Small nuclear RNA gene on chromosome 1 (120,850,819 to 120,850,985, reverse strand). Ensembl gene ENSG00000275538.
Gene Ontology:
Molecular function: pre-mRNA 5'-splice site binding
Biological process: mRNA 5'-splice site recognition
Cellular component: U1 snRNP
Homologues: Paralogues in human: RNU1-1 (92% identical), RNU1-2 (92% identical), RNU1-27P (92% identical), RNU1-28P (92% identical), RNU1-3 (92% identical), RNU1-4 (92% identical), RNVU1-18 (92% identical), RNVU1-29 (92% identical), U1 (92% identical), RNVU1-28 (91% identical), RNVU1-7 (91% identical), RNVU1-31 (90% identical), and 134 more.